TWIST1 (twist family bHLH transcription factor 1)
Diseases named in the same sentence as TWIST1 in open-access papers (continued):
Sharing a sentence is not in itself a finding about the gene and the disease.
Saethre-Chotzen syndrome (continued). "Lineage tracing reveals an embryonic Six2+ osteoprogenitor population that contributes to the postnatal suture mesenchyme, with these progenitors being preferentially affected in a Twist1+/−; Tcf12+/− mouse model of Saethre-Chotzen Syndrome." (PMID 34376651, 2021). "Correspondingly, in Twist1+/−; Tcf12+/− mutants, a robust model for Saethre-Chotzen Syndrome coronal synostosis, Erg+/Six2+ progenitors were reduced as early as E14.5 yet ectocranial populations were relatively unaffected." (PMID 34376651, 2021). "Heterozygous Twist1 knockout mice showed craniofacial and limb abnormalities, mimicking clinical features of Saethre-Chotzen syndrome patients." (PMID 32655411, 2020). "Mutations in FGFR2 have not been shown to cause lineage mixing within the suture mesenchyme; however, both the En1−/− mouse model and the Twist1+/− mouse model of Saethre-Chotzen syndrome demonstrate extensive lineage mixing leading to coronal suture fusion." (PMID 32916911, 2020). "In future studies, it will be important to explore the stage-specific role of TWIST1 and characterize more detailed mechanisms of musculoskeletal symptoms in Saethre-Chotzen syndrome." (PMID 32011235, 2020). "Taken together, we concluded that the Twist1-F191S mutant mouse manifests some features of the Saethre-Chotzen syndrome." (PMID 32051525, 2020). "In Saethre-Chotzen syndrome, mutations in transcription factor 12 (TCF12) or twist-related protein 1 (TWIST1) genes ablate the coronal suture, as observed in human and rodent studies." (PMID 31828085, 2019). "The Saethre-Chotzen syndrome (SCS) is an autosomal dominant craniosynostosis characterized by facial and limb deformities caused by loss-of-function mutations of the TWIST1 gene on chromosome 7p21." (PMID 28521820, 2017). "Loss of function mutations in the bHLH domain in one allele of the TWIST1 gene cause Saethre-Chotzen Syndrome (SCS) in humans, an autosomal dominant craniofacial disease caused by gene haploinsufficiency, denoting the functional importance of the TWIST1 bHLH domain." (PMID 22891766, 2012). "Pathologically, Twist1 is a master regulator of epithelial-to-mesenchymal transition (EMT) and is causative of the autosomal-dominant human disease Saethre Chotzen Syndrome (SCS)." (PMID 18855684, 2008). "Misregulation of TWIST1 dimerization with HAND2 is caused by mutations of phosphoresidues in the PKA consensus domain or in the bHLH domain, which have been reported to be associated with Saethre-Chotzen syndrome." (PMID 35781329, 2022). "Inversion prone position effects are not only limited to other species, it has also been reported in some human disease conditions, such as aniridia (PAX6), campomelic dysplasia (SOX9), familial adenomatous polyposis (APC) and Saethre-Chotzen syndrome (TWIST1)." (PMID 31191618, 2019). "In Saethre-Chotzen syndrome, mutations in TCF12 or TWIST1 ablate a specific suture, the coronal." (PMID 30375332, 2018). "In four cases, patients’ phenotypes well matched to the syndromic features caused by haploinsufficiency of PAX6 (Aniridia, MIM:607108), TCF4 (Pitt-Hopkins syndrome, MIM:610954), FBN1 (skeletal/joint malformations, limb deformity; MIM:154700), and TWIST1 (Saethre-Chotzen syndrome, MIM:101400)." (PMID 27257017, 2016). "Twist1 mutant mice exhibit coronal synostosis and mimic features of Saethre-Chotzen syndrome." (PMID 20175913, 2010). "More specifically, haploinsufficiency of Twist1, using Twist1 (+/−) mouse mutants, results in coronal synostosis and in turn a widened skull in the left-right lateral direction with a shortening in its anterior-posterior length, similarly reflecting the phenotype of Saethre-Chotzen syndrome." (PMID 33842480, 2021).
Saethre-Chotzen syndrome (continued). "Twist1 molecularly interacts with Sox10, and although Twist1 S192P displays a comparatively reduced interaction with Sox10 (asterisk, 48.3%+/−5.1%, p-value = 0.002), Twist1 T125;S127A, a Saethre-Chotzen Syndrome-associated Helix I dimerization mutant, does not (102.7%+/−12.0%, p-value = 0.85)." (PMID 23555309, 2013). "TWIST1-mediated EMT has been shown to be important in the context of various cancers, and mutations in the TWIST1 gene are also associated with the genetic developmental disorder Saethre-Chotzen syndrome (SCS)." (PMID 41246007, 2025). "Genes associated with the other syndromes (e.g., Carpenter [RAB23 gene, MEGF8 gene], Apert [FGFR2 gene], Crouzon [FGFR2 gene], Pfeiffer [FGFR2 gene, FGFR1 gene], and Saethre-Chotzen syndromes [TWIST1 gene]) were analyzed by WES analysis and none of these mutations were found on the patients." (PMID 34348791, 2021).
pancreatic cancer (54 papers, 2011 to 2026). "Our results revealed that Twist1 blockade in combination with vorinostat in pancreatic cancer cells suppresses EMT‐associated genes and the immune checkpoint VISTA compared to treatments administered alone." (PMID 40344465, 2025). "Many researchers have shown that the expression of Twist1 is associated with poor clinical outcomes and distal metastasis in various solid cancer types such as prostate, cervical, breast, gastric, and pancreatic cancers." (PMID 33808323, 2021). "In addition, Twist1 has been shown to be associated with cell proliferation, invasion and migration in pancreatic cancer." (PMID 40344465, 2025). "As a result, identifying the genes associated with EMT in pancreatic cancer and understanding the role of Twist1 in this process is a crucial step to contribute to the identification of new targets for pancreatic cancer treatment and the improvement of existing treatment strategies." (PMID 40344465, 2025). "Another study has shown that high expression of Twist1 in pancreatic cancer is associated with poor prognosis and that Twist1 may be an important regulator of the Warburg effect." (PMID 40344465, 2025). "We also sought to determine the synergistic effects of an HDACi, vorinostat, in combination with Twist1‐siRNA on VISTA expression in pancreatic cancer cells’ viability and proliferation." (PMID 40344465, 2025). "In the current study, we found that Twist1 is an important regulator of the immune checkpoint VISTA in pancreatic cancer." (PMID 40344465, 2025). "Our data show that the use of the chromatin modifier vorinostat upregulates Twist1 gene expression in pancreatic cancer cell lines." (PMID 40344465, 2025). "Subsequently, a combination of vorinostat treatment and Twist1‐siRNA transfection was applied to pancreatic cancer cells for 48 h." (PMID 40344465, 2025). "Specifically, vorinostat treatment significantly upregulated Twist1 gene expression in all three pancreatic cancer cell lines." (PMID 40344465, 2025). "The combination of Twist1‐siRNA and vorinostat given to pancreatic cancer cell lines has significantly reduced cell viability in CAPAN‐1 cells compared to other cells when used alone." (PMID 40344465, 2025). "After determining the IC50 values through MTT analysis, the viability of pancreatic cancer cells was examined following the combined application of vorinostat and Twist1‐siRNA." (PMID 40344465, 2025). "As early as 2013, it was found that Twist family BHLH transcription factor 1 (TWIST1) was hypermethylated in pancreatic cancer." (PMID 37403096, 2023). "Recent studies have found that TWIST1 promotes the Warburg metabolism of pancreatic cancer by transcriptionally regulating glycolytic genes." (PMID 37403096, 2023). "Our study found that miR-532 also inhibited cell proliferation and metastasis by targeting TWIST1 in pancreatic cancer." (PMID 37403096, 2023). "Not surprisingly, TWIST1 plays a regulatory role in the proliferation, migration, invasion, and EMT of pancreatic cancer cells, and TWIST1 is involved in the regulation as a miRNA target in these reports." (PMID 37403096, 2023). "miR-539 targeting Twist1 inhibited the growth of pancreatic cancer xenografts in nude mice, as well as attenuated the migration and invasion of pancreatic cancer cells in vitro." (PMID 35805066, 2022). "have found the prognostic value of the combination of oxoglutarate dehydrogenase like (OGDHL), TWIST1 and miR-214 in predicting pancreatic cancer patients." (PMID 35651786, 2022). "The model simulations proposed the proteins AURKA, CD44, PAK1, STAT3, and TWIST1 as promising therapeutic targets for pancreatic cancer." (PMID 33578795, 2021). "The gene expression analysis of EMT markers Zeb1, Vimentin, and Col1a1 were significantly decreased in YFP sorted primary pancreatic cancer cell lines from KPC;ST mice, along with complete loss of Snai1 and Twist1." (PMID 33852841, 2021).
pancreatic cancer (continued). "In fact, pharmacological inactivation of the Twist1 function showed promising effects of protecting cancer-induced cachexia, with a significant survival benefit in the experimental model of pancreatic carcinoma." (PMID 32655411, 2020). "Specifically, the Msh homeobox protein (MSX2) is a downstream target of the Ras signaling pathway and is suggested to induce Twist1 expression in human pancreatic cancer cells." (PMID 28099910, 2017). "HIF-2α contributes to VM formation by regulating the expression of VE-cadherin through the binding of the transcription factor Twist1 to the promoter of VE-cadherin in pancreatic cancer both in vitro and in vivo." (PMID 28599281, 2017). "After two weeks, we observed the tumor volume and investigated the expression of VM, Twist1, and VE-cadherin in the murine pancreatic tumor tissues." (PMID 28599281, 2017). "The results showed that Twist1 and Twist2 expressions were located in the cytoplasm of pancreatic cancer cells." (PMID 26842802, 2016). "Interestingly, studies have observed hypermethylation in the promoter region of Twist1 in pancreatic cancer." (PMID 40344465, 2025). "Furthermore, the combination application of vorinostat, which is commonly used in cancer therapy, with the blockade of Twist1 in pancreatic cancer has substantially downregulated VISTA expression." (PMID 40344465, 2025). "Our findings also indicate that VISTA expression in pancreatic cancer correlates positively with Twist1, suggesting that this mechanism may play an important role in pancreatic cancer progression and sensitivity to immunotherapy." (PMID 40344465, 2025). "Our study confirmed that miR-532 induces autophagy in pancreatic cancer cells through TWIST1, and the KEAP1/NRF2 pathway may be its downstream target gene." (PMID 37403096, 2023). "In addition, gene expression correlation with that of TWIST1 is also observed in the bladder cancer thyroid carcinoma and pancreatic cancers, when analyzed using TCGA dataset." (PMID 37534184, 2023). "Further investigation revealed that LZTS1-AS1 may exert a positive effect on pancreatic cancer by regulating TWIST1 through sponge miR-532." (PMID 37403096, 2023). "Changes in TWIST1 level could portend a poor prognosis in TCGA cohorts of several cancer settings.TWIST1 modulates aerobic glycolysis in pancreatic cancer cells by increasing the expression of key glycolytic genes, including HK2 and PKM2." (PMID 36176750, 2022). "Furthermore, based on our previous study that FHL3 regulated the Akt/GSK3β/ubiquitin-Snail1|Twist1 pathway to stabilize the EMT-TFs to promote EMT process in pancreatic cancer, we explored the role of FHL3 in the regulation of ubiquitin-mediated EMT." (PMID 34150617, 2021). "In addition, we confirmed that the overexpression of HIF-2α increased Twist1 expression and promoted tumor growth and VM formation in pancreatic cancer xenografts in nude mice." (PMID 28599281, 2017). "However in pancreatic cancer cells, Twist1 promotes invasion and cisplatin resistance by inducing GDF15 expression by increasing p38 MAPK activity." (PMID 28099910, 2017). "Twist1 expression was observed in hGBMs as well as in medulloblastoma, meningioma, lung and pancreatic cancer specimens, while Sox2 expression was observed in hGBM specimens along with that of meningioma, lung and pancreatic cancers." (PMID 22184289, 2011). "Therefore, targeted therapeutic approaches targeting Twist1 may help prevent critical processes such as tumour progression, metastasis, and chemotherapy resistance in pancreatic cancer." (PMID 40344465, 2025). "However, TWIST1 is hardly expressed in pancreatic cancer cells." (PMID 38904009, 2024). "However, whether the relationship among autophagy, EMT, and stable TWIST1 is the key to tumor proliferation and metastasis in pancreatic cancer remains to be further explored." (PMID 37403096, 2023).
pancreatic cancer (continued). "Following the Twist1‐siRNA transfection, a noticeable decrease in the expression levels of EMT‐related genes was observed in Mia PaCa‐2 and AsPC‐1 pancreatic cancer cells." (PMID 40344465, 2025). "In this study, we investigated the effects of Twist1 and the HDAC inhibitor vorinostat on VISTA expression levels in pancreatic cancer." (PMID 40344465, 2025). "In pancreatic cancer, SOX6 downregulates TWIST1 by recruiting HDAC1 to the TWIST1 promoter, which inhibits pancreatic cancer metastasis." (PMID 38331879, 2024). "In this study, TWIST1 was also involved in the regulation of EMT and autophagy in pancreatic cancer." (PMID 37403096, 2023). "have discovered the crucial role of Aurora Kinase A (AURKA)-Twist1 axis in promoting EMT and chemoresistance of pancreatic cancer." (PMID 35651786, 2022). "Numerous transcription factors have been identified as regulating pancreatic cancer growth, including SMAD3 and TWIST1, among others." (PMID 36090038, 2022). "We found that in pancreatic cancer cells, Twist1 interacts with Ring1B and EZH2 to regulate the expression of E-cadherin and p16 protein, thereby promoting the metastasis of pancreatic cancer." (PMID 33569740, 2021). "In contrast, TWIST and SNAIL dampen the response to gemcitabine in an autochthonous mouse model of pancreatic cancer as Snai1 and Twist1 knockout results in prolonged survival in gemcitabine‐treated tumor mice." (PMID 34459003, 2021). "Our in vitro data confirmed previous studies which demonstrated its role in the EMT of pancreatic cancer cells as well as its cellular downstream effects by targeting ZEB1 and TWIST1." (PMID 31080555, 2019). "On the other hand, in contrast to the Snail1 and Twist1 knock-outs, ZEB1 knock-out suppressed the metastatic dissemination of primary tumor cells using the same KPC pancreatic cancer model." (PMID 30463358, 2018). "In the present study, we found that Twist1, Twist2 and E-cadherin were regulated by HIF-2α in pancreatic cancer cells." (PMID 26842802, 2016). "Therefore, in this study, we aim to investigate the genes that are associated with EMT and explore the potential mechanism involving Twist1, a proto‐oncogene, and VISTA in pancreatic cancer." (PMID 40344465, 2025). "We first show that Twist1 and VISTA are highly expressed in pancreatic cancer, and we then focused on the effects of EMT, examining the role and mechanisms of Twist1 and HDAC inhibition on proliferation, migration, and the impact on VISTA in human pancreatic cancer cell lines." (PMID 40344465, 2025). "This is due to the fact that deletion of Snail1 and Twist1 genes in pancreatic cancer did not directly attenuate metastasis, but conversely increased chemoresistance in mouse transgenic models." (PMID 35805066, 2022). "However, the efficacy of PAK1, TWIST1, or CD44 inhibition for pancreatic cancer treatment will have to be determined in further pre-clinical and clinical studies." (PMID 33578795, 2021). "Interestingly, TWIST1 and AURKA have very recently been seen to form a feedback loop promoting metastasis and highly aggressive phenotypes in pancreatic carcinoma, and TWIST1 is a marker for EMT in neuroendocrine tumours." (PMID 29757368, 2018). "In pancreatic cancer, deletion of mouse Twist1 did not halt the invasion, systemic dissemination or metastasis of pancreatic ductal adenocarcinoma (PDAC), but sensitized tumors to gemcitabine in vivo." (PMID 28099910, 2017). "Clinical tissues IHC staining showed that Twist2 and E-cadherin expression had an obviously negative correlation in pancreatic cancer tissues, however, it had no obvious correlation between Twist1 and E-cadherin." (PMID 26842802, 2016).